HRAS (HRas proto-oncogene, GTPase)
Diseases named in the same sentence as HRAS in open-access papers (continued):
Sharing a sentence is not in itself a finding about the gene and the disease.
melanoma (continued). "However, targeting HRAS might be limited by development of resistance as seen for BRAF inhibitors in melanoma." (PMID 26544513, 2015). "Finally, as a model more closely related to melanoma, primary human melanocytes were analysed that had been engineered to become tumourigenic by defined genetic modifications, i.e. hTERT, large T antigen and HRAS." (PMID 23666755, 2013). "Another cancer that depends on NF-κB activity is melanoma, as it could be shown that HRas-mediated initiation of tumorigenesis requires IKK2-mediated NF-κB activation in a mouse model of melanoma and even for lung cancer it could be demonstrated that IKK2 and NF-κB are crucial cofactors." (PMID 23915189, 2013). "However, these epidemiological data do not reveal the mechanisms by which HRAS rs12628 SNP modifies melanoma risk." (PMID 22618666, 2012). "PLEKHA5-L upregulates oncogenes (e.g., HRAS, AKT3) to enhance melanoma migration and proliferation, while concomitantly elevating the expression of therapy-resistance mediators PD-L1 and ABC transporters." (PMID 40356756, 2025). "However, mutations in NRAS (~30%), but not KRAS (3%) or HRAS (2%), are common in melanomas." (PMID 36901857, 2023). "Molecular testing for common melanoma driver genes, including BRAF, NRAS, KRAS, HRAS, NF1, and KIT, was available for this study." (PMID 37686691, 2023). "Upon examining the new attention map post the removal of high-attention genes, we discern that the model now places more attention on genes HRAS, AKT2, PIK3CA for melanoma." (PMID 37932419, 2023). "While KRAS is the overall dominant gene that is coaltered, HRAS contributed to most coalteration cases in bladder cancer, and NF1 coalteration preferably occurs in melanoma and endometrial cancer." (PMID 33507258, 2021). "These genomic subtypes include BRAF-mutant melanoma (50%), NRAS, KRAS and HRAS-mutant melanoma (25%), NF1-mutant melanomas (15%) and triple wild-type melanomas (10%)." (PMID 34572747, 2021). "The findings revealed that three Nitroglycerin genes (EGFR, HRAS and MAPK3) were found to be common in 4 types of cancers viz Bladder cancer, Endometrial cancer, Melanoma and Non-small cell lung cancer." (PMID 34764329, 2021). "In LN, MAPK3 (cf = 53), PIK3R1 (cf = 51), HRAS (cf = 46), PIK3R2 (cf = 45) and KRAS (cf = 44) are the top 5 cross-talk genes, and as expected most of these are already recognized melanoma markers." (PMID 26558755, 2015). "The oncogenic RAS genes in melanoma cells include NRAS, KRAS, and HRAS." (PMID 36901857, 2023). "To accomplish this, we tested, at early and late passages, the most common genes, including HRAS, NRAS, and BRA, known to induce early-stage melanoma transformation and which are not mutated in mel-CSP." (PMID 37047372, 2023). "These subtypes are represented by BRAF mutant melanomas, which account for approximately 50% of melanomas; NRAS-, KRAS-, and HRAS-mutant melanomas, which are about 25%; NF1-mutant melanomas (15% of melanomas); and triple-wild-type melanomas, which account for the remaining 10% of cases." (PMID 35563772, 2022). "HRAS mutations have been shown on multiple occasions to aid in distinguishing Spitz nevus from Spitz melanoma, as HRAS is almost never present in melanoma." (PMID 35747831, 2022). "A closer look revealed that the essentiality of IGF1R was significantly higher in NRAS‐mutant cell lines compared with NRAS‐WT background and also generally in BRAF WT melanoma cell lines, which is mainly composed of NRAS and HRAS mutants, compared with the BRAF V600E mutants." (PMID 33073517, 2020). "NGS revealed 118 (26%) of 446 melanomas with no mutation, 42% with BRAF mutations, 25% with NRAS mutations, 4.9% with KIT mutations, and 2.0, 2.7 and 2.7% with HRAS, KRAS and PIK3CA mutations, respectively." (PMID 31277584, 2019).
melanoma (continued). "The genomic landscape of melanoma, performed by The Cancer Genome Atlas (TCGA) on 333 melanoma samples delineated 4 genomic subtypes, i.e., triple wild-type (WT), BRAF mutant, NRAS, HRAS or KRAS mutant, and NF1 mutant, as well as three transcriptomic subclasses, i.e., immune, keratin and MIFT-low." (PMID 29743104, 2018). "It is also possible that NRAS may activate different signaling pathways from KRAS and HRAS, an idea supported by the observation that NRAS has greater transforming activity than KRAS in experimental models of melanoma." (PMID 29349077, 2017). "Mutations were also identified in brain metastases from non-breast primaries in EGFR (3/9 - 33%; two lung and one kidney), HRAS (1/9 - 11%; lung), KRAS (2/9 - 22%; one colon and one lung), NRAS (3/9 - 33%; two lung and one kidney) and PIK3CA (2/9 - 22%; one melanoma and one lung)." (PMID 20604919, 2010). "The findings were identical and included the demonstration that 14 genes including the HRAS gene (ENSG:00000174775) were expressed in the skin of body as melanoma-related genes, and identified 102 RIKEN bioresources were expected to be relevant to melanoma research, such as RBRC10866 and RBRC01088." (PMID 40380154, 2025). "The distribution of HRAS codon mutations varied by cancer type, with a higher prevalence of HRAS G13 mutations in HNSCC (42/112, 37.5%), squamous NSCLC (41/90, 45.6%), and melanoma (22/55, 40%) and a higher prevalence of Q61 mutations in non-squamous NSCLC (18/34, 52.9%) compared to other mutations." (PMID 38672653, 2024). "We further classified the 89 samples into the four molecular subtypes, BRAF mutated (47% in melanoma TCGA), RAS mutated (NRAS/KRAS/HRAS mutations, 29%), NF1 mutated (9%), and Triple-WT (subgroup lacking above mutations, 15%), proposed by the recent TCGA melanoma cohort." (PMID 30373548, 2018). "Additionally, when we plotted the top 65 DEGs, we noticed that sample clustering was independent of mutations in the RAS (KRAS, NRAS, and HRAS) and NF1 genes, which have been described to modify gene expression patterns in melanoma, avoiding expression bias that might be caused by those genes." (PMID 30242167, 2018).
bladder cancer (84 papers, 2005 to 2025). "The evidence is also available that TP63+ bladder cancers, which all bear either HRAS or NRAS mutations, are particularly sensitive to RAF1 pathway inhibition." (PMID 39678505, 2024). "In contrast, 27.2% of HRAS-mutant bladder cancers carried a co-altered MAPK mutation compared to 23% and 44% of KRAS and NRAS, respectively." (PMID 37503077, 2023). "Such HRAS mutations have been consistently observed in several types of cancer, including squamous cell carcinoma of the head and neck, bladder cancer, and thyroid carcinoma." (PMID 37153521, 2023). "Mutations in HRAS have been observed in various cancers, including bladder cancer, pancreatic cancer, and lung cancer." (PMID 37153521, 2023). "Nearly 15% of cases of bladder cancer have a mutation of HRAS, and the active HRAS protein contributes to the tumor progression and is associated with the risk of recurrence." (PMID 33036162, 2020). "Oncogenic HRAS activation seems to be tightly associated with the promotion of tumorigenesis in human bladder cancer." (PMID 30875794, 2019). "More recently, a combination of methylation status of TWIST, ONECUT2, and OTX1 with mutational analyses of FGFR3, TERT, and HRAS has been reported to detect bladder cancer with a sensitivity of 97% and a specificity of 83%." (PMID 29907142, 2018). "Somatic mutations in HRAS have been found to be associated with bladder cancer, thyroid carcinoma, salivary duct carcinoma, epithelial-myoepithelial carcinoma, and kidney cancers." (PMID 29021294, 2017). "The HRAS G12V mutation is predominant in bladder cancer which was detected in the T24 bladder cancer cell line." (PMID 26544513, 2015). "HRAS mutations are frequent with about 2.8 – 5.1% in lung and bladder cancer, however, rather infrequent in endometrium and esophageal cancer with about 1% each." (PMID 26544513, 2015). "The G4-decoys repressed HRAS transcription and caused a strong antiproliferative effect, mediated by apoptosis, in T24 bladder cancer cells where HRAS is mutated." (PMID 21931711, 2011). "As 80% of bladder tumors harbor HRAS mutations and more than half of bladder tumors overexpress HRAS, both mutation and overexpression are important factors in the tumorigenesis of bladder cancer." (PMID 21931711, 2011). "The same authors have shown that increased hypomethylation in the HRAS promoter was inversely associated with lower expression in bladder cancer, suggesting that other genetic or epigenetic factors may contribute to HRAS-mediated tumorigenesis." (PMID 39858030, 2025). "Similarly, in bladder cancer, HRAS mutations have been detected in 1%–2% of cases and are associated with high-grade tumours and advanced disease." (PMID 37153521, 2023). "Mutations in HRAS are found in bladder cancer and can serve as a tumor staging function." (PMID 36430344, 2022). "HRAS as proto-oncogene was associated with Costollo syndrome – a congenital disorder characterized by coarse face, loose skin, cardiomyopathy and predisposition to tumors such as benign papillomas or malign rhabdomyosarcomas, neuroblastoma and bladder cancer." (PMID 26544513, 2015). "Given the crucial role of HRAS overexpression and mutations in the tumorigenesis of bladder cancer, one attractive therapeutic strategy could be to inhibit HRAS transcription with molecules that are able to impair the activity of the gene promoter." (PMID 21931711, 2011). "Moreover, the aberrant activation of HRAS during bladder cancer development may be caused by the demethylation of the HRAS promoter." (PMID 36430344, 2022). "Biopsies from bladder cancer patients have shown a significant positive association between hypomethylation of KRAS, NRAS, and HRAS promoters and their expression levels." (PMID 39858030, 2025).
bladder cancer (continued). "Previous study showed that mutations in HRAS, KRAS, and NRAS exist in approximately 30% of human cancers, with HRAS mutations being more common in bladder cancer compared to the other two67." (PMID 37704624, 2023). "The KEGG bladder cancer pathway activation in poor prognosis CRCs was mostly due to increased expression of functional nodes HRAS/KRAS/NRAS, ARAF/BRAF/RAF1, MAPK1/MAPK3, and RPS6KA5." (PMID 36316649, 2022). "HRAS mutations have been mainly documented in HNSCC, salivary glands, pheochromocytoma and bladder cancers." (PMID 35621690, 2022). "This study has discovered that miRNA-1184 interacts with KRAS, NRAS, and HRAS coding genes, thereby regulating their effect in bladder cancer." (PMID 34234808, 2021). "We also identified the RAS oncogene family (KRAS, NRAS, and HRAS) as a bladder cancer stimulus factor." (PMID 34234808, 2021). "Pterostilbene further decreased tumor growth in mice that received cisplatin plus gemcitabine, suggesting a potentially chemotherapeutic role of pterostilbene for cisplatin treatment of human bladder cancers with oncogenic HRAS." (PMID 33036162, 2020). "In 2017, the first report of a human TERT promoter-driven GAL4/upstream activating sequence (UAS) binding system for selective activation of CRISPR/Cas9 targeting the HRAS oncogene in bladder cancer cells was published." (PMID 31035374, 2019). "This is important because confirmation of “oncogene addiction” (reviewed in14,15) to mutant HRAS or interrelated components of the FGFR3 or PI3K/AKT/mTOR pathways would allow development of targeted approaches to treat noninvasive bladder cancer." (PMID 30670749, 2019). "HRAS lies downstream of FGFR3, and increased signaling following mutations in HRAS are correlated with enhanced susceptibility to bladder cancer and other abnormalities in patients with Costello syndrome." (PMID 30670749, 2019). "Remarkably, treatment of J82 bladder cancer cells that carry oncogenic HRAS with romidepsin leads to increased apoptosis (controlled by ERK-pathway activation and ROS production), as compared to the parental J82 cells that host wild-type RAS genes." (PMID 30875794, 2019). "We have shown that mutant HRAS is a potential drug target in different types of cancer including lung cancer and bladder cancer." (PMID 26544513, 2015). "In the present study, we investigated HRAS downstream signaling in five different cancer cell lines including lung and bladder cancer and putative drugs for targeted therapy." (PMID 26544513, 2015). "HRAS mutation conferred MEK sensitivity in lung cancer of adenocarcinoma and squamous origin, bladder cancer, endometrium cancer and squamous esophageal cancer cell lines." (PMID 26544513, 2015). "HRAS gains have been found in bladder cancer cell lines and have been related to urothelial tumorigenesis." (PMID 26202601, 2015). "In summary, in this study we shed light on how HRAS transcription is regulated and how G4-DNA specific binders repress oncogenic HRAS in urinary bladder cancer cells." (PMID 25013182, 2014).
bladder cancer (continued). "We also report that the two quadruplex structures can function as targets for therapeutic molecules designed to repress oncogenic HRAS in bladder cancer cells." (PMID 25013182, 2014). "Genetic studies of bladder cancer have a rich history, including the identification of the first oncogene, HRAS, in a bladder carcinoma cell line." (PMID 23593348, 2013). "Following this transcription model we designed several decoy oligonucleotides in quadruplex conformation eliciting a potent antiproliferative effect in T24 urinary bladder cancer cells bearing mutant HRAS." (PMID 21931711, 2011). "We have therefore developed a multiplex mutation assay for the detection of the most frequently occurring HRAS, KRAS, and NRAS mutations in bladder cancer." (PMID 21072204, 2010). "HRAS, a GTPase, is commonly mutant in head and neck, thyroid, and bladder cancer." (PMID 39844043, 2025). "RAS is the most frequently mutated oncogene in bladder cancer, with KRAS, HRAS, and NRAS involved." (PMID 39678505, 2024). "However, our gene analysis results reveal that pterostilbene-induced autophagy has the potential to sensitize HRAS mutant bladder cancer cells to cisplatin, suggesting the pterostilbene-induced autophagy is cytotoxic." (PMID 33036162, 2020). "Based on data in The Cancer Genome Atlas (TCGA), HRAS expression was significantly higher in clinical bladder cancer samples compared to healthy samples and samples from patients without the HRAS mutation." (PMID 33036162, 2020). "Indeed, creation of the Upk2-HRAS* model of bladder cancer confirmed a role for mutant HRAS in noninvasive bladder cancer." (PMID 30670749, 2019). "HRAS is a proto-oncogene involved in the tumorigenesis of urinary bladder cancer." (PMID 21931711, 2011). "However, although mutation of HRAS as well as FGFR3 and PI3K/AKT/mTOR components are associated with development of noninvasive bladder cancer, it is unknown if the hyperplastic and/or transformed state depends upon maintenance of oncogene expression." (PMID 30670749, 2019). "Three cell lines, including H1299 (lung cancer), A549 (lung cancer), and T24 (bladder cancer), harboring the NRAS, KRAS, and HRAS oncogene, resp., were transfected with the PY4- -Luciferase and Ranila plasmids." (PMID 34172933, 2021). "This pathway is activated in around 40% bladder cancer cases (FGFR3: > 10%, EGFR:> 10%, ERBB2:~ 10%, ERBB3:~ 10%, NRAS/HRAS/KRAS:~ 10%, PTEN: ~ 10%, AKT3:~ 10%)." (PMID 31665050, 2019).
bladder cancer (continued). "The antiproliferative activity of the designed G4-decoys was tested in two types of cells: HeLa and T24 urinary bladder cancer cells that harbour a mutant HRAS [codon 12 GGC (Gly) is changed in GTC (Val)], expressing a hyperactivated HRAS protein." (PMID 21931711, 2011). "For example, enhanced tumour growth correlated with increased AMPK and fatty acid oxidation in ovarian cancer cells, linked to dysregulation of mTORC1 expression in renal cell carcinoma and has been connected to the hypoxia and oncogenic HRAS or KRAS pathways in glioblastoma and bladder cancer." (PMID 37697969, 2023). "Interestingly, these pathways are downstream of the EGFR and ErbB2 family proteins whose expression and activity are related to bladder cancer progression, as well as ErbB3, FGFR3 and HRAS that are active in superficial tumors." (PMID 23383328, 2013). "Unlike bladder carcinomas, the most affected genes are FGFR3, HRAS, and KMT2D." (PMID 39064555, 2024).